GPR75 (G protein-coupled receptor 75)
Diseases named in the same sentence as GPR75 in open-access papers (continued):
Sharing a sentence is not in itself a finding about the gene and the disease.
Alzheimer disease (2 papers, 2020 to 2025). A progressive, neurodegenerative disease characterized by loss of function and death of nerve cells in several areas of the brain leading to loss of cognitive function such as memory and language. "As such, future studies of the therapeutic value of GPR75 antagonists on disease states such as ischemic stroke, Alzheimer's disease and vascular dementia should be explored." (PMID 33013649, 2020). "Activation of GPR75 by CCL5 was reported to attenuate the neurotoxic effect of amyloid-β, which is a hallmark of Alzheimer's disease." (PMID 33013649, 2020). "CYP4A and GPR75 expression in the hippocampus, entorhinal cortex and corpus callosum may play a role in Alzheimer's disease and vascular dementia." (PMID 33013649, 2020). "Therefore, it will be prudent to examine GPR75 antagonists as potential neuroprotective therapies for Alzheimer's disease and cerebrovascular disease." (PMID 33013649, 2020).
diabetes (2 papers, 2022 to 2025). "Although it is implicated in the pathogenesis of diabetes by promoting immune cell recruitment through activation of C-C chemokine receptors (CCRs), RANTES/CCL5 also shows beneficial effects on β-cells through the activation of the G-protein-coupled receptor 75 (GPR75)." (PMID 35628332, 2022).
hepatocellular carcinoma (2 papers, 2024 to 2025). A malignant tumor that arises from hepatocytes. "In contrast, GPR75 mRNA dramatically increased in hepatocellular carcinoma samples." (PMID 39959811, 2024).
steatosis (2 papers, 2024). Increased lipid within the cytoplasm of cells. "We observed a significant upregulation of GPR75 mRNA in steatosis and steatohepatitis and a substantial downregulation of mRNA in liver cirrhosis." (PMID 39959811, 2024).
Anxiety (1 paper, 2024). Intense feelings of nervousness, tension, or panic often arise in response to interpersonal stresses. "Additionally, it has been reported that GPR75 plays a role in regulating hippocampal activity, and Gpr75-knockout mice display altered contextual memory and anxiety-like behaviors." (PMID 39137039, 2024).
cardiac hypertrophy (1 paper, 2025). "In this study, blocking the 20-HETE/GPR75 axis with AAA significantly reversed Ang II-induced cardiac hypertrophy." (PMID 39825084, 2025). "Notably, this research was the first to highlight the significant role of the novel 20-HETE receptor, GPR75, in Ang II-induced cardiac hypertrophy." (PMID 39825084, 2025). "Inhibition of 20-HETE synthesis or blockade of its receptor, G-protein-coupled receptor 75 (GPR75), significantly reversed Ang II-induced cardiac hypertrophy." (PMID 39825084, 2025). "Moreover, blocking GPR75 with AAA replicated the effects of 20-HETE inhibition, significantly suppressing Ang II-induced ROS generation and Ca2+/CaN/NFAT3 pathway activation, ultimately reversing Ang II-induced cardiac hypertrophy." (PMID 39825084, 2025).
Cognitive impairment (1 paper, 2020). Abnormal cognition is characterized by deficits in thinking, reasoning, or remembering. "Expression in these regions could have a functional significance that may help explain cognitive impairment and white matter changes observed in human studies examining CYP4A genetic variants and studies in animals examining GPR75's role in neurodegeneration and amyloid-β accumulation." (PMID 33013649, 2020).
depression (1 paper, 2024). "In summary, these findings underscore the role of GPR75 in mediating CSDS-induced depression-like behavior and cellular stress responses of microglia." (PMID 38890305, 2024).
eosinophilia (1 paper, 2025). "CCL5 regulates a variety of immune cells, including the transport of T cells, monocytes, eosinophilia, etc., which can bind to at least four receptors, including CCR1, CCR3, CCR5 and GPR75, among which CCR5 is the main receptor of CCL5 in adipose tissue." (PMID 40725440, 2025).
GM1 gangliosidosis (1 paper, 2020). A rare lysosomal storage disorder characterized biochemically by deficient beta-galactosidase activity and clinically by a wide range of variable neurovisceral, ophthalmological and dysmorphic features. "Importantly, no up-regulation in Gpr75 protein levels or CHOP translocation was detected in control GM1 gangliosidosis patient fibroblasts following lentivirus-mediated transduction with the GFP reporter gene." (PMID 31481471, 2020).
Insulin resistance (1 paper, 2024). Increased resistance towards insulin, that is, diminished effectiveness of insulin in reducing blood glucose levels. "In addition, several studies also indicated that deficiency in GPR75 protects against the onset of insulin resistance." (PMID 39137039, 2024). "Previous studies have suggested that 20-HETE impairs insulin signaling through GPR75 activation and contributes to the development of insulin resistance." (PMID 39137039, 2024).
malignant hypertension (1 paper, 2025). Severe hypertension that is characterized by rapid onset of extremely high blood pressure and hypertension-mediated organ damage. "In an Ang II-dependent malignant hypertension model using Cyp1a1-Ren-2 transgenic rats, blocking GPR75 with AAA effectively reversed I3C-induced malignant hypertension, which is associated with reduced Ang II levels in plasma and kidneys." (PMID 40362321, 2025).
non-alcoholic fatty liver disease (1 paper, 2025). "Under HFD conditions, Gpr75 knockout mice exhibited lower food intake, increased physical activity, lower liver weight, and decreased hepatic triglyceride and lipid levels, suggesting that Gpr75 deletion protects against non-alcoholic fatty liver disease (NAFLD)." (PMID 40362321, 2025).
open-angle glaucoma (1 paper, 2025). Chronic outflow obstruction of the eye's drainage canals that can lead to increased internal eye pressure and optic nerve damage. "Additional research has linked the 2p16 region, where GPR75 is located, to autosomal dominant juvenile primary open-angle glaucoma (POAG) in two large Chinese families." (PMID 40362321, 2025).
prostate adenocarcinoma (1 paper, 2021). "In contrast, in prostate adenocarcinoma tissues, UCP2 expression is reduced, while several MAM-stabilizing proteins, including AKAP1, RICTOR, GPR75, and PEMT1, were found to be upregulated." (PMID 33614647, 2021).
Stroke (1 paper, 2019). Sudden impairment of blood flow to a part of the brain due to occlusion or rupture of an artery to the brain. "Nevertheless, whether GPR75 and GPR40 play a role in the vascular effects of 20-HETE in stroke in unknown." (PMID 31514409, 2019).
cancer (5 papers, 2021 to 2025). A tumor composed of atypical neoplastic, often pleomorphic cells that invade other tissues. "Notably, expression levels of proteins facilitating mitochondrial-ER interaction, including AKAP1, RICTOR, Rab32, PACS2, GPR75, and PEMT1, were reduced in these cancer tissues." (PMID 33614647, 2021).
cardiovascular disease (5 papers, 2023 to 2025). "Collectively, these studies strongly suggest GPR75’s involvement in cardiovascular diseases, particularly in blood pressure regulation and endothelial function." (PMID 40362321, 2025).
metabolic disorders (1 paper, 2024). "Ultimately, targeted therapies based on GPR75 could offer novel strategies for the prevention and treatment of MASLD and other metabolic disorders." (PMID 39310267, 2024).
GPR75 also shares sentences with these, for which no sentence is quoted: tumor (4 papers); portal hypertension (2); age-related macular degeneration (1); cerebrovascular disease (1); hearing loss (1); hypertrophy (1); insulinoma (1); ischemic stroke (1); liver cirrhosis (1); metastatic prostate carcinoma (1); neuroblastoma (1); neurological disorders (1); non-small cell lung carcinoma (1); vascular dementia (1).